CXCL8 (C-X-C motif chemokine ligand 8)
Diseases named in the same sentence as CXCL8 in open-access papers (continued):
Sharing a sentence is not in itself a finding about the gene and the disease.
cancer (continued). "This demonstrated potential in using [99mTc]Tc-CXCL8 for detecting neutrophil recruitment in cancer and therapeutic response." (PMID 34637051, 2022). "CXCL-8 is a small soluble C-X-C chemokine that functions in chronic inflammation and cancer development." (PMID 36567905, 2022). "C‐X‐C motif chemokine legend 8 (CXCL8) is a signalling molecule elevated in the cancer setting both systemically and within the TME of several solid tumour types." (PMID 35879507, 2022). "IL-8, synonymous with CXCL8, signals through the receptors CXCR1 or CXCR2, is a neutrophil chemokine, is elevated in the common cancers, and contributes to their associated angiogenesis, and epithelial-to-mesenchymal transition." (PMID 35626167, 2022). "Antibody-based neutralization of CXCL8 blocked neutrophils chemotaxis elicited by the conditioned media of MTX-treated cancer cells, to the same extent as that of the untreated cells or MTX-treated cells in the presence of KIRA6." (PMID 34453119, 2022). "Growing evidence has revealed the crucial role of CXCL8-CXCR1/2 axis in the TME and prognostic significance of the CXCL8 serum level in human cancer, following immune checkpoint blockade therapy." (PMID 36091114, 2022). "Recent studies have documented that CXCL8 promoted migration, invasion, and proliferation of human cancer cells through EMT induction through the PI3K/AKT/NF-κB signaling axis." (PMID 34025668, 2021). "Some clinical investigations suggest that CXCL8 plays a significant role in cancer development, including GC." (PMID 34680333, 2021). "Interleukin-8 (IL-8) also known as C-X-C motif chemokine ligand 8 (CXCL8), shows pleiotropic roles in cancer settings, including promotion of angiogenesis, epithelial-mesenchymal transition (EMT), immunosuppression and metastasis." (PMID 34168563, 2021). "In this context, neutralizing antibodies against CXCR1, CXCR2, or CXCL8 suppressed the migration and invasion in a human ESCC cancer cell model induced by CXCL8." (PMID 33390169, 2021). "Some of these genes were also present in the general cancer pathway, including NFkBIA, IL-6 and CXCL8." (PMID 34680349, 2021). "Immunohistochemistry of clinical samples confirmed that the expression of CXCL8 and 10 was higher in three cancer tissues." (PMID 34439306, 2021). "In the sight of the clinical significance and biological function of the CXCL8-CXCR1/2 signal transduction axis in cancer, it has been suggested that CXCL8 and its receptors are considered as attractive targets for cancer treatment." (PMID 34025668, 2021). "It has been reported that CXCL8 inhibits the cell communication between cancer tissue and stroma, as well as the angiogenesis activity of endothelial cells." (PMID 34869316, 2021). "The secretion and production of chemokines such as CCL2, CXCR1/2, CXCL12, CXCR4, and CXCL8 play critical roles in cancer development and subsequent metastasis." (PMID 34530822, 2021). "A new subset of CD10+GPR77+CAFs induce cancer stem cells’ (CSCs) enrichment and chemoresistance by secreting IL-6 and CXCL8 in cancer." (PMID 35011369, 2021). "The smallest cluster (labeled CXC-1) was enriched for cells expressing CXC motif ligands such as CXCL1, CXCL2, and CXCL8, which are thought to stimulate cancer cell proliferation and migration." (PMID 34611171, 2021). "IL-8, also known as CXCL8, is a major chemokine that promotes the infiltration of polymorphonuclear leukocytes into tissue; IL-8 has also been found to be involved in cancer progression." (PMID 34868992, 2021). "The genes (CXCL1, CXCL3, CXCL8, NFKBIB, and SRC) associated with chemokine pathway signaling result in changes in the cellular microenvironment that favor cancer and transformation in L-LVL cells." (PMID 34680563, 2021). "USP17 is induced by the stromal cell-derived factor-1 (SDF-1)/C-X-C motif chemokine ligand 12 (CXCL12) and IL-8/CXCL8 chemokines in cancer cells." (PMID 34454495, 2021).
cancer (continued). "CXCL8 can be secreted by fibroblasts, CAFs, endothelial cells, epithelial cells, DCs, monocytes, macrophages, and cancer cells." (PMID 35011369, 2021). "Senescent human fibroblasts can secrete IL-6 and CXCL8 to promote cancer cell invasion and metastasis." (PMID 35011369, 2021). "Initially recognized for its property of controlling leukocyte chemotaxis, secreted CXCL8 is now also known for its significant role in human cancer-related angiogenesis." (PMID 34299365, 2021). "CTX also inhibits chemokines that bind to CXCR1 and CXCR2 receptors such as CXCL5, CXCL1/2/3, CXCL1a, CXCL6, and CXCL8 (IL-8) that are involved in cancer angiogenesis and metastasis." (PMID 34822613, 2021). "Collectively, our data suggested CXCL8 up-regulation as a novel potential diagnostic biomarker in CRC patients of different races, cancer stages, genders, age groups, and body weights." (PMID 34473751, 2021). "The results confirm that the L-HCV genes CXCL8 and SRC are positively linked with cancer-promoting genes." (PMID 34680563, 2021). "Among chemokines, IL-8 (CXCL8) stimulates the migration of neutrophils to the site of inflammation and also the migration of cancer cells facilitating the metastatic process." (PMID 32973970, 2020). "The pleiotropic effects on CXCL8 in cancer prompted investigations also on markers of angiogenesis and autophagy." (PMID 31924241, 2020). "Our experiments demonstrate that cancer cells stimulate the proliferation of fibroblasts and educate them to express pro-angiogenic proteins CXCL8 and CCL2." (PMID 32214219, 2020). "For example, administration of the anti-cancer reagent induced CXCL8 production, and the expression of the receptors of CXCL8, CXCR1 and CXCR2." (PMID 32766720, 2020). "The results indicated that some crucial cancer-related pathways were related to the high expression of CXCL8 and E2F1 and the low expression of CYP2C8, which was consistent with the expression level results and prognostic results." (PMID 32851080, 2020). "In the present study, a high expression of MMP-9 in cancer tissues was observed by immunohistochemistry, and there was a positive correlation with the increase of CXCL8 expression." (PMID 32201645, 2020). "Robust upregulation of CXCL8 (aka IL-8) has been observed in erlotinib-resistant cell lines which also makes it a cancer therapy target." (PMID 32085733, 2020). "The increased expression of CXCL8 induced by anti-cancer drugs, such as doxorubicin and cisplatin, can upregulate the expression of ATP-binding cassette transporters, resulting in poor chemotherapeutic response." (PMID 33198757, 2020). "We identify carcinoma-educated fibroblasts as the source of angiogenesis via secretions of CXCL8 (aka IL-8) and CCL2 (aka MCP-1)." (PMID 32214219, 2020). "All these indicate that CXCL8 can be utilized as a prognostic and predictive cancer biomarker to indicate a more aggressive phenotype." (PMID 31681401, 2019). "We proceeded to perform quantitative ELISA to measure CXCL8 levels in conditioned media collected from cancer cells treated with shNS or shPTPRD." (PMID 31805999, 2019). "However, the detailed mechanisms underlying CXCL8‐mediated cancer progression may be diverse." (PMID 31304688, 2019). "For example, it has been reported that CXCL1, a functional homologue of CXCL8 in mice, recruits CD11b+ Gr1+ myeloid cells in vivo, which contributes to the cancer progression." (PMID 31147602, 2019). "In conclusion, the here reported results, would suggest a further anti-cancer effect of PLX4720 which is manifested by its ability to reduce CXCL8 secretion." (PMID 30867499, 2019). "In Cytokine-cytokine receptor interaction pathways, CXCL8 was illustrated to be highly relevant to cancer." (PMID 32038715, 2019).
cancer (continued). "CXCL8 is the most studied chemokine in human cancer in view of its multiple pro-tumorigenic properties, which span from induction of cell growth to promotion of metastatic processes." (PMID 31762942, 2019). "Since then, several studies reported that CXCL8 is also secreted by a wide variety of cancer cell lines including those derived from well-differentiated papillary, medullary, and anaplastic thyroid cancer." (PMID 31762942, 2019). "The authors concluded that the release of certain mediators (i.e., CXCL8/IL-8) lead MCs to improve the acquisition of mesenchymal and stem-like characteristics of TC cells, therefore fostering cancer progression." (PMID 31500315, 2019). "TAMs have been observed to express PD-L1 and induce immune evasion of cancer through autocrine CXCL8." (PMID 30885276, 2019). "The binding of CXCL8 to CXCR2 in cancer cells facilitates metastasis, which was also observed in MDA-MB-231 cells and xenograft mouse models with CXCR2-knockout, as well as decreased migration, compared with wild-type cells." (PMID 31788042, 2019). "We and other have shown that IL-6 and CXCL8/IL-8 play a critical role in the epithelial to mesenchymal transition of human carcinoma cells." (PMID 31741710, 2019). "The results of these studies indicated that the concentrations of CXCL8 are higher in cancer patients compared with healthy controls." (PMID 29977225, 2018). "CXCL8, also known as IL‐8, is a chemokine that modulates cancer cell proliferation, invasion, and migration of multiple cancers." (PMID 29808619, 2018). "Moving from the idea that lowering the levels of CXCL8 would result in the attenuation of its pro-tumorigenic effects, several attempts were done to reduce CXCL8 production by cancer cells or to block its effects." (PMID 29977225, 2018). "In xenografted and orthotopic in vivo models of cancer, the metastatic potential of many solid tumors was found to be positively related with the secretion of CXCL8." (PMID 29977225, 2018). "The results obtained with CXCL8 neutralizing mAb were consistently confirmed by studies aimed at lowering the secretion of CXCL8 by cancer cells." (PMID 29977225, 2018). "With this aim, several studies measured the concentrations of CXCL8 in the serum and in tissues of cancer patients." (PMID 29977225, 2018). "Several pro-inflammatory cytokines and their associated pathways, which are known to promote cancer cell proliferation in many cases, were implicated in typical responders throughout this study, including IL6, CCL20, CXCL8, TNF signaling, and IL-17 signaling." (PMID 29983870, 2018). "Following its secretion by cancer cells, CXCL8 can enhance their proliferation rate and survival through autocrine signaling pathways." (PMID 29977225, 2018). "Recently, it has been reported that CXCL8 exerts potent pro-tumoral effects in malignant context, such as angiogenesis, cancer stem cells proliferation, and attraction of immunosuppressor cells." (PMID 30568862, 2018). "For instance, a phase Ib pilot study is undergoing to assess HuMax-CXCL8, a CXCL8 neutralising antibody, in patients with metastatic or unresectable, locally advanced malignant solid tumors." (PMID 30486864, 2018). "These CXCL8-induced changes were characterized in cells deriving from cancers of the colon, of the nasopharynx, and of the breast." (PMID 29977225, 2018). "On the other hand, the neutrophil chemotactic chemokines, CXCL-1 and CXCL-8, have been shown to be pro-tumorigenic and pro-angiogenic by their ability to recruit pro-tumorigenic neutrophils into cancer tissue." (PMID 29387062, 2017). "Previous reports revealed that CXCR1 knockdown reduces chemotherapy-induced CRT exposure in cancer cells, and that CXCL8 facilitates formation of the CRT/CXCR1 complex." (PMID 28938588, 2017). "CXCL8 has been considered to be a biomarker for various cancer types, and high serum level of CXCL8 levels in cancer patients is associated with poor prognosis." (PMID 29147073, 2017).
cancer (continued). "A high expression level of CXCL8 in TAMs and ESCC cancer cells was strongly associated with poor prognosis through lymph node metastasis." (PMID 29285315, 2017). "Recently, pharmaceutical agents that have the potential to suppress CXCL8 expression are being investigated for the potential use in cancer treatment." (PMID 29147073, 2017). "CXCL8 (encoding IL-8) activates EGF and MAPK signaling cascades resulting in cancer progression and metastasis in diverse cancer types." (PMID 28038442, 2017). "For further exploration, we selected five genes that have been previously experimentally demonstrated in other cancer setting in humans, CXCL8/IL8, UHRF1, BRCA1, MCM10, and CDKN3." (PMID 26859141, 2016). "With specific regard to cancer, the activation of several oncogenes further modulates the release of CXCL8." (PMID 27555670, 2016). "Combined, these results indicate that both mouse and human ASCs are chemoattracted to CXCL1, as well as to CXCL8 secreted by cancer cells." (PMID 27241286, 2016). "These genetic alterations activate, in a RAS-BRAF-MAPK-dependent manner, transcription of proinflammatory molecules like VEGF-A, CXCL1/GRO-α, CXCL10/IP-10, and CXCL8/IL-8, which can act autocrinously or paracrinously to support cancer cell growth and survival." (PMID 27213120, 2016). "Silencing IGF-2 or STAT3 expression in cancer cells or IGF-2R or CXCL8 expression in stromal cells significantly inhibits the cancer–stroma communication and vascular endothelial cells' angiogenic activities." (PMID 26465273, 2015). "CXCL8 (IL-8) has been demonstrated to be involved in cancer stem cell biology and cancer cell metastasis." (PMID 26328269, 2015). "During cancer growth, vascularization is a key factor to support the development of tumors, wherein CXCL8 induces endothelial growth through CXCR1 and CXCR2 signaling." (PMID 26087179, 2015). "The experiments revealed that the mediators of each aspect of cancer cell behavior are diversified: proliferation was driven by IL-6, migration by CXCL8 and CCL2, invasion by IL-6, MMP-3 and uPA, and EMT by TGF-β1." (PMID 26284488, 2015). "Taken together, these results indicate that MCs, by releasing specific mediators, including CXCL8/IL-8, enhance the acquisition of mesenchymal and stem-like features of TC cells, thus promoting cancer progression." (PMID 26379707, 2015). "Like IL-12, CXCL8 expression levels correlated with disease progression in several human carcinomas." (PMID 26649771, 2015). "CXCL8 also plays an important role in the migration of leucocytes and metastasis of cancer cells in HCC microenvironment 34–36, although the function of CXCL8 needs to be further clarified." (PMID 24268047, 2014). "This dose also effectively blocked CXCL8/IL-8 expression in the cancer cells, and COX2 expression in the tumors, as determined by western blot analyses." (PMID 24924428, 2014). "Particular attention has been paid to CXCL8 (IL-8), which is highly expressed in a large number of cancer types." (PMID 24782982, 2014). "This evidence indicates that CXCL8, produced in an inflammatory microenvironment, aggravates the inflammatory state and enables cancer cells to survive and to migrate from the primary site." (PMID 24224100, 2013). "In various types of human cancers, high levels of CXCL8 in serum or at local sites correlate with aggressive disease and poor initial response to drugs, including oxaliplatin, 5-fluorouracil, paclitaxel, and camptothecin." (PMID 24224100, 2013). "Focal adhesion kinase (FAK) and Src-kinases are also activated in cancer cells stimulated with CXCL8." (PMID 24224100, 2013). "CXCL8 is secreted from a range of cell types including leukocytes, fibroblasts, endothelial cells and malignant cancer cells." (PMID 24276377, 2013).
cancer (continued). "The remainder of this review will focus on elucidating some of the principal strategies available for targeting CXCL8-CXCR1/2 signaling in cancer, both indirectly with the use of anti-inflammatories, and directly, using CXCL8- or CXCR1/2-targeted inhibitors." (PMID 24276377, 2013). "In this respect, the regulators, receptors, signaling pathways, and effectors of chemokines such as CXCL8 provide attractive targets for cancer therapeutic intervention." (PMID 24224100, 2013). "In contrast, paclitaxel, camptothecin, and erlotinib increase CXCL8 transcription and secretion in cancer cells (and our unpublished data)." (PMID 24224100, 2013). "CXCL8 is a chemotactic cytokine with important functions during acute inflammation as well as in the context of various cancers." (PMID 24250750, 2013). "The potentiation of CXCL8 expression by 1,25(OH)2D3 will lead to an initially more pronounced inflammatory reaction, which, dependent on the type of cancer, will either have an supporting or disadvantageous effect on cell survival." (PMID 24250750, 2013). "CXCL8 is one of the dominant transcriptional targets of the inflammatory signaling mediated by nuclear factor-κB (NF-κB), which is commonly activated in cancer cells." (PMID 24224100, 2013). "In cancer models of the liver, pancreas, colorectum, and melanoma, CXCL8 functions as an autocrine growth factor." (PMID 24224100, 2013). "Despite this extensive pre-clinical literature, there has been limited exploitation of this knowledge in clinical trials aimed at evaluating anti-CXCL8 or CXCR1/2 inhibitors as anti-cancer therapeutics." (PMID 24276377, 2013). "Other questions are: (a) if the primary cancer cells utilize CXCL8- (and/or other cytokine) mediated mechanisms to migrate and establish a metastatic site, would further expression of these chemokines at the new site be essential?" (PMID 24224100, 2013). "In each case, administration of the anti-cancer agent was shown to induce CXCL8 expression and secretion, as well as expression of the CXCR1 and CXCR2 receptors." (PMID 24276377, 2013). "Due to its potent angiogenic effects and the activity of the chemokine and its receptors in the promotion of invasion and metastasis, CXCL8 and its receptors are now considered as attractive targets for cancer therapy." (PMID 24224100, 2013). "Among the cytokine related pathways, high expression of VEGF, CXCL8, CXCR2, and CXCL1 are associated with cancer metastasis and progression." (PMID 22479608, 2012). "IL-8, a member of the CXC chemokine family also known as CXCL8, can function as a mitogenic, angiogenic, and mutagenic factor promoting cancer progression." (PMID 22069560, 2010). "Furthermore, polymorphisms in genes encoding members of both CXCL8:CXCR1/2 and the VEGF:VEGFR signaling axes are linked to morbidity and response to anti-VEGF therapy in angiogenic diseases, including AMD and cancers." (PMID 41176546, 2025). "CXCL1, CXCL2, CXCL5, and CXCL8 attract neutrophils that overexpress CXCR2 to cancer-prone tissues." (PMID 40134607, 2025). "By prolonging the presence of engineered chemokine mutants in the bloodstream and optimizing their stability, these strategies aim to enhance the therapeutic efficacy of CXCL8-based interventions, offering promising avenues for the treatment of several CXCL8-mediated pathologies, including cancer." (PMID 40124384, 2025). "CXCL8 levels were significantly higher in serious cancer patients." (PMID 39660100, 2025). "Recently, CXCL8 has also been recognized as an important gene promoting angiogenesis, which may provide a necessary basis for facilitating cancer progression and metastasis." (PMID 39741182, 2025). "In addition to metabolic interactions, CAF-conditioned medium induced greater CXCL8 release from cancer cells than NF-conditioned medium." (PMID 41444422, 2025).